MMP13 (matrix metallopeptidase 13)
Diseases named in the same sentence as MMP13 in open-access papers (continued):
Sharing a sentence is not in itself a finding about the gene and the disease.
Parkinson disease (2 papers, 2020 to 2022). A progressive degenerative disorder of the central nervous system characterized by loss of dopamine producing neurons in the substantia nigra and the presence of Lewy bodies in the substantia nigra and locus coeruleus. "In turn, MMP13 directly alters microglia supporting the need for multi-target therapies to treat Parkinson's disease patients." (PMID 33343280, 2020).
scoliosis (2 papers, 2017 to 2025). A congenital or acquired spinal deformity characterized by lateral curvature of the spine. "Moreover, it has been shown that MMP13 was highly upregulated in a rat‐induced scoliosis model." (PMID 40337077, 2025).
spinal tuberculosis (2 papers, 2021 to 2023). "Increased expression of MMP13 has been reported in patients with spinal tuberculosis." (PMID 35153741, 2021).
spondyloepimetaphyseal dysplasia (2 papers, 2015 to 2022). An osteochondrodysplasia that results in abnormalities of bone growth in the vertebral column, epiphysis, and metaphysis. "Our results may also help clarify the etiology of the altered snouts of mice with mutations in genes known to affect resorption such as Mmp2, and jaw length defects in humans with conditions such as Juvenile Paget’s disease (i.e., Opg) and Spondyloepimetaphyseal dysplasia (i.e., Mmp13)." (PMID 26449912, 2015).
systemic sclerosis (2 papers, 2012 to 2025). A chronic disorder, possibly autoimmune, marked by excessive production of collagen which results in hardening and thickening of body tissues. "Furthermore, increased serum levels of MMP-13 have been reported in conjunction with systemic sclerosis in humans, further supporting its relevance in fibrosis." (PMID 22911824, 2012).
ulcerative colitis (2 papers, 2015 to 2023). An inflammatory bowel disease involving the mucosal surface of the large intestine and rectum. "Mmp3, Mmp10, and Mmp13 mRNA levels were significantly upregulated in ulcerative colitis and colorectal adenocarcinoma compared with the levels of normal cohorts." (PMID 25742789, 2015).
vasculitis (2 papers, 2020 to 2021). "The following potential proteases for the different CKD aetiologies were identified: ADPKD (MMP7), MCD (CTSB, CTSD, CTSE, MEP1A, MMP7, PGA3), MGN (MMP3, MMP7, MMP9, MMP13, MMP14), IgAN (MMP7), FSGS (MMP3, MMP7), vasculitis (PGA3), nephritis (MMP7, MMP9), nephrosclerosis (MMP7), and DKD (MMP9)." (PMID 32427855, 2020).
vitamin D deficiency (2 papers, 2020 to 2023). A nutritional condition produced by a deficiency of VITAMIN D in the diet, insufficient production of vitamin D in the skin, inadequate absorption of vitamin D from the diet, or abnormal conversion of vitamin D to its bioactive metabolites. "Patients with sufficient vitamin D levels had lower MMP-1 and MMP-13 levels compared to patients with vitamin D insufficiency (p < 0.001 and p < 0.001, respectively)." (PMID 36845046, 2023). "Vitamin D deficiency accelerates degradation of the articular cartilage by inducing transforming growth factor- β, matrix metalloproteinases (MMP) -9 and MMP-13." (PMID 32303230, 2020).
, and neck cancer (1 paper, 2022). "Indeed, expression of MMP-13 had been reported in various tumors including colorectal, prostate, esophageal, breast and head, and neck cancer (HNSCC)." (PMID 36713871, 2022).
Achilles tendinitis (1 paper, 2018). "In addition, the local injection of SIM/PMSs into the tendons of collagenase-induced Achilles tendinitis rat models suppressed pro-inflammatory cytokines (MMP-3, COX-2, IL-6, TNF-α, and MMP-13)." (PMID 29534523, 2018). "In order to investigate the in vivo anti-inflammatory effects of SIM/PMSs on collagenase-induced Achilles tendinitis models, we monitored the mRNA levels of both pro-inflammatory cytokines (MMP-3, COX-2, IL-6, TNF-α, and MMP-13) and anti-inflammatory cytokines (IL-4, IL-10, and IL-13)." (PMID 29534523, 2018).
actinic keratosis (1 paper, 2004). A precancerous lesion of the skin composed of atypical keratinocytes. "Although MMP-1, -2, -3 have been detected in actinic keratosis, premalignant and benign tumors were mostly negative for MMP-13 in one study." (PMID 15291964, 2004).
acute coronary syndrome (1 paper, 2023). Signs and symptoms related to acute ischemia of the myocardium secondary to coronary artery disease. "The deceased were older, had more manifest acute coronary syndrome (ACS), a lower left ventricular ejection fraction (LVEF), and an estimated glomerular filtration rate (eGFR), but significantly higher MMP13, TIMP-1, hs-CRP, and NT-proBNP compared with the survivors." (PMID 38162139, 2023).
adenomatous colon polyp (1 paper, 2015). A polypoid adenoma that arises from and protrudes into the lumen of the colon. "In precancerous conditions, MMP-13 expression varies among target organs, being overexpressed in adenomatous colon polyps, but not present in premalignant lesions of the skin." (PMID 26193700, 2015).
adenomyosis (1 paper, 2022). The growth of endometrial tissue inside the muscular wall of the uterine corpus. "Increased MMP1 and MMP13 were detected in the endometrium of women with versus without adenomyosis (P = 0.018 and P = 0.031)." (PMID 35773139, 2022).
aortic atherosclerosis (1 paper, 2018). A atherosclerosis that involves the aorta. "We previously found that NOS3 prevents aortic atherosclerosis in mice, at least by regulating the expression of MMP-13, by yet unknown mechanisms." (PMID 30347750, 2018).
Aortic dissection (1 paper, 2022). Aortic dissection refers to a tear in the intimal layer of the aorta causing a separation between the intima and the medial layers of the aorta. "It has been reported that when aortic dissection occurs, the serum levels of MMP1, MMP2, MMP3, MMP8, and MMP13 are increased, and the expression of MMP9 in the cytoplasm of smooth muscle cells in the aortic wall is enhanced." (PMID 35463768, 2022).
Atrophy (1 paper, 2025). Any weakening or degeneration, especially through lack of use. "In both cases, IL-17 signaling is amplified, which drives extracellular matrix degradation (via upregulation of Mmp3/Mmp13) that culminates in colonic atrophy." (PMID 40356657, 2025).
Barrett's metaplasia (1 paper, 2010). "No data are currently available which connect expression of MMP-1 and MMP-13 with Barrett's metaplasia and related EACs with the tumor proliferation model of multistep carcinogenesis and clinicopathologic features." (PMID 20946664, 2010).
Blindness (1 paper, 2025). Blindness is the condition of lacking visual perception defined as a profound reduction in visual perception. "Furthermore, C. albicans infection in the cornea has been shown to stimulate ocular angiogenesis through MMP13, potentially resulting in vision impairment or blindness." (PMID 41249582, 2025).
brain tumor (1 paper, 2024). "The protein expression of MMP9, MMP13, TIMP1, TIMP2, and TIMP4 was elevated in all three investigated brain tumor diagnoses." (PMID 38474106, 2024). "As the genes for MMP1 and MMP13 were not amplified in the control samples, it was not possible to determine the fold change in these genes in the examined brain tumors." (PMID 38474106, 2024).
Chagas disease (1 paper, 2020). A parasitic infection caused by Trypanosoma cruzi. "Because myocardial expression of Mmp12 and Mmp13 that are encoded by macrophages was maximally increased, we also performed co-localization studies to examine whether macrophages contribute to profibrotic response in Chagas disease." (PMID 32098116, 2020).
Cholestatic liver disease (1 paper, 2021). "Whether concurrent inhibition of MMP-1 and MMP-13 can act synergistically with ADAM17 remains uncharacterized in cholestatic liver disease." (PMID 35095853, 2021).
Chronic colitis (1 paper, 2023). A chronic inflammatory disease of the large intestine (colon, cecum and rectum). "Similar to the gene expression data in human samples, we observed that MMP13 was increased on RNA and protein level in a well-established mouse model of chronic colitis and intestinal fibrosis." (PMID 37207229, 2023).
chronic venous insufficiency (1 paper, 2022). Chronic form of venous insufficiency (disease). "In the skin of patients affected by severe chronic venous insufficiency (CVI), an elevated gene expression for MMP-1, MMP-2, MMP-9, and MMP-13 has been demonstrated." (PMID 35456498, 2022).
colon adenoma (1 paper, 2023). An adenoma that arises from the colon. "Interestingly, only Mmp7 and Mmp13 displayed a significantly higher level of activation in colon adenomas compared with both the adjacent tissue (13.8- and 13.4-fold increase, respectively) and colon tissue with acute colitis (186.4- and 19.6-fold increase, respectively)." (PMID 36901742, 2023).
corneal ulceration (1 paper, 2015). "The role of MMP13 has been described in Pseudomonas aeruginosa induced corneal ulceration." (PMID 26053426, 2015).
craniosynostosis (1 paper, 2021). Craniosynostosis is defined as the premature fusion of one or more cranial sutures leading to secondary distortion of skull shape resulting in skull deformities with a variable presentation. "If we used 31 genes associated with craniosynostosis of any suture in mice, only the Mmp13-expressing osteoblast populations were enriched significantly." (PMID 34880220, 2021). "Significant enrichment of craniosynostosis gene expression also was found in the Mmp13-expressing osteoblast (CS6-3 and CS8-5) population." (PMID 34880220, 2021).
dentin dysplasia (1 paper, 2022). Dentin dysplasia (DD) is a rare disorder belonging to the group of hereditary dentin defects and is characterized by abnormal dentin structure and root development resulting in abnormal tooth development. "Within this study, the observed dental phenotype in Mmp13−/− mice had similarities to certain hereditary dentin-defects, traditionally subdivided into three types of dentinogenesis imperfecta (DI) and two of dentin dysplasia." (PMID 35531096, 2022).
diabetic kidney disease (1 paper, 2024). Progressive kidney disorder caused by vascular damage to the glomerular capillaries, in patients with diabetes mellitus. "Our findings also suggest a regulatory role of miRNAs in modulating target genes such as AKT1, MMP13, and IGF1R, implicating them in signaling pathways and cellular metabolism relevant to Diabetic Kidney Disease." (PMID 38891851, 2024).
diabetic retinopathy (1 paper, 2024). "A different study demonstrated that elevated levels of MMP-13 in human monocytes were associated with hyperglycemic conditions, suggesting that this enzyme might contribute to diabetic retinopathy through its action in myeloid cells." (PMID 38576768, 2024). "In diabetic retinopathy, the activation of the runt-related transcription factor 2 pathway highlighted MMP13 as one of the putative target proteins for this diabetic complication." (PMID 38576768, 2024).
diverticulitis (1 paper, 2024). An infection that develops in the diverticula of the intestinal tract. "Whilst a collagen deficit does not identify individuals who will go on to develop diverticulitis, one study demonstrated downregulation of MMP2, MMP9 and MMP13 expression and an increase in MMP1, TIMP1 and TIMP3 in inflamed mucosa of patients with diverticulitis versus Crohn’s disease." (PMID 38831715, 2024).
edema (1 paper, 2021). An abnormal accumulation of fluid beneath the skin, or in one or more cavities of the body. "Our results suggest a reduced expression of pro-inflammatory cytokines including TNF-α, IL-6, IL-1β, and MMP-13 in the ASPP 092 treated ear of the mice in a dose-dependent manner when compared to that of the EPP-induced ear edema mice those are untreated." (PMID 34588910, 2021).
emphysema (1 paper, 2013). "On the one hand MMP-13 may still help to limit ECM deposition in areas of dense fibrosis, on the other hand excessive MMP-13 activities in the airways may promote development of honeycomb cysts, similar to the induction of emphysema formation in MMP-1 overexpressing mice." (PMID 24023851, 2013).
endotoxemia (1 paper, 2013). "The depletion of mucus by pilocarpine treatment resulted in sensitization for LPS-induced shock both in MMP13+/+ and MMP13−/− mice, which further strengthens the notion of the important role of the mucus layer in endotoxemia." (PMID 23723167, 2013). "Early after endotoxemia induction, we observed strong up-regulation of MMP13 in all tested organs." (PMID 23723167, 2013).
esophageal adenocarcinoma (1 paper, 2010). A malignant tumor with glandular differentiation arising predominantly from Barrett mucosa in the lower third of the esophagus. "Expression of MMP-13 was negative in tumor specimen and in the esophageal adenocarcinoma cell line OE-33, but was rarely detected in stromal cells (data not shown)." (PMID 20946664, 2010).
Fever (1 paper, 2023). Body temperature elevated above the normal range. "The concentration of MMP-2, MMP-3, MMP-9, MMP-13, TIMP-1, and FG-α in the KD group were significantly higher than those in the fever group (p < 0.05).The KD group was divided into two subgroups, patients with combined CAL and 179 patients without combined CAL." (PMID 37575991, 2023). "The concentration of MMP-2, MMP-3, MMP-9, MMP-13, TIMP-1, and FG-α in the KD group were significantly higher than those in the fever group (p < 0.05)." (PMID 37575991, 2023).
Fibroadenoma (1 paper, 2021). A benign tumor of the breast characterized by the presence of stromal and epithelial elements. "Similarly, no MMP-13 expression has been reported in normal mammary gland and benign mammary lesion (0/9) and in several normal tissues including uterus, liver, prostate, parotid gland, breast, fibroadenomas." (PMID 34452576, 2021).
fibrosarcoma (1 paper, 2021). A malignant mesenchymal fibroblastic neoplasm affecting the soft tissue and bone. "The ethanol extract of baked Gardeniae fructus inhibited the expression of MMP9 and MMP13, thereby suppressing the migration and invasion of human fibrosarcoma cells." (PMID 34643237, 2021).
fluorosis (1 paper, 2024). "The Col1a1, Bcl2, Fgfr1, Mmp9, Mmp13, Bmp2, and Bmp7 genes are the key regulatory factors in fluorosis bone metabolism." (PMID 39125380, 2024).
gallbladder cancer (1 paper, 2023). "Moreover, the upregulation of NEDD4L enhances the transcription of MMP1 and MMP13, leading to aggressive gallbladder cancer." (PMID 38027016, 2023). "In addition, NEDD4L overexpression may lead to gallbladder cancer invasion by decreasing the transcription of MMP1 and MMP13." (PMID 38027016, 2023).
gastric tumors (1 paper, 2010). "Gene ontology analysis of gene expression in the gastric tumors indicates that PPARδ, MMP12, MMP13, Cxcl1, Cxcl5, S100A8, and S100A9 share both common and disparate pathway interactions that likely contributed to the tumorigenic phenotype." (PMID 21318167, 2010).
gastrointestinal stromal tumor (1 paper, 2024). "Therefore, to further verify the role of EFNA1 combined with MMP13 in the diagnosis of GC, it is necessary to conduct retrospective studies on multi-centers, large samples, and multiple tissue types [such as gastric malt and Gastrointestinal stromal tumors (GIST)]." (PMID 38987376, 2024).
giant cell tumor of bone (1 paper, 2011). "In particular, the stromal cells of giant cell tumor of bone (GCT) express very high levels of MMP-13 in response to the cytokine-rich environment of the tumor." (PMID 21461405, 2011).
glomerulosclerosis (1 paper, 2021). A hardening of the kidney glomerulus caused by scarring of the blood vessels. "We observed that several components of SASP known to play a potential role in glomerulosclerosis, such as PAI‐1, IL‐1β, IL‐6, or MMP13, were upregulated in kidneys of old mice as compared to young mice." (PMID 34725920, 2021).
gout (1 paper, 2022). A condition characterized by painful swelling of the joints, which is caused by deposition of urate crystals. "Reducing uric acid levels, inhibiting inflammation, and decreasing the expression of MMP13 may be responsible for the therapeutic effect of PEL, which suggests that PEL can be further developed as a drug for the treatment of gout." (PMID 35449811, 2022).
HCMV infection (1 paper, 2020). "In particular, HCMV infection led mainly to the over-expression of CCL2, CCL3, CCL11, CXCR4, IL-1β, IL13, MMP1, MMP3, MMP9 and MMP13, SERPINA1, TNFα, and BMP7, and the gradual and constant downregulation of IL13RA2 (up to almost 800-fold at 14 days p.i.)." (PMID 32899126, 2020).
hemarthrosis (1 paper, 2016). Bleeding into the joints. "We had previously established that in the multiple injury model of hemarthrosis (Day 30/60/75/90), factors that contribute to hypoxia (HIF-1α, 3.3–6.5-fold), angiogenesis (VEGF-α, 2.5–4.4-fold) and chondrocyte damage (matrix metalloproteinase 13 (MMP13), 2.8–3.8-fold) were significantly elevated." (PMID 27070581, 2016).
hepatic granuloma (1 paper, 2018). A granuloma located in the liver. "To further explore the mechanism by which the LV-gra15II-M alleviated hepatic granulomas and fibrosis, we investigated the MMP13 expression both in vitro and in vivo." (PMID 30034399, 2018).
Hyperkeratosis (1 paper, 2011). Hyperkeratosis is a histopathological term defining a thickened stratum corneum and may be present in many different skin conditions, with many possible overlaps. "It would seem from our immunohistological examinations that the additional delay in wound healing observed in the Mmp13;Plau double-deficient mice is a result of hyperkeratosis, leading to a compressed build-up of keratinocytes under the skin surface." (PMID 21326869, 2011).
Hypertension (1 paper, 2013). The presence of chronic increased pressure in the systemic arterial system. "Our findings suggest that in addition to MMP-2 and -9, MMP-13 is also likely to regulate ECM remodeling in hypertension." (PMID 24159376, 2013). "In addition to MMP-2 and MMP-9, we demonstrate that MMP-13 also plays a significant role in hypertension-induced renal injury." (PMID 24159376, 2013).
lentivirus infection (1 paper, 2021). Virus diseases caused by the Lentivirus genus. "Immunofluorescence experiments further revealed that OA progression, as assessed primarily by MMP13, ADAMTS4, and COL2A1, was inhibited in HCs following circRSU1 shRNA lentivirus infection." (PMID 33408787, 2021).
leprosy (1 paper, 2013). Leprosy is a chronic infectious disease affecting primarily the skin and peripheral nervous system. "Expression of MMP3, MMP13, CCL22 were seen to be highest in PBMC cultures of healthy contacts as compared to leprosy types." (PMID 23936569, 2013).
limb ischemia (1 paper, 2011). A ischemia that involves the limb. "After 3 days of limb ischemia following femoral artery ligation, MMP-2, MMP-3, and MMP-13 were increased in diabetic mice compared to controls, but collagenolysis was decreased, indicating a suppression of the response." (PMID 22214528, 2011).
lipid metabolic disorders (1 paper, 2024). "The reduction and inactivation of STAT3 lead to lipid metabolic disorders and promote triglyceride accumulation by upregulating the mRNA levels of ELOVL7, PPARG, MMP1, MMP13, and TIMP4, and downregulating the mRNA level of PTGS2." (PMID 39125712, 2024).
metastasis (1 paper, 2020). The spread or migration of cancer cells from one part of the body (where they first appeared) to another. "Increased mRNA expression of LPHN3 and MMP13 was significantly associated with axillary node metastasis assessed by RT-PCR." (PMID 33247693, 2020).
neuralgia (1 paper, 2023). "This is the first report that has revealed that the MMP-13 inhibitor, i.e., CL-82198, reverses the DNP-associated neuralgia effects." (PMID 37259308, 2023).